Y_RNA (Y RNA )
Gene: Miscellaneous RNA gene on chromosome 2 (127,829,747 to 127,829,852, reverse strand). Ensembl gene ENSG00000200390.
Homologues: Orthologues: chimpanzee Y_RNA (100% identical), macaque Y_RNA (79% identical). Paralogues in human: Y_RNA (84% identical), RNY3 (83% identical), Y_RNA (83% identical), Y_RNA (82% identical), Y_RNA (81% identical), RNY3P1 (80% identical), Y_RNA (80% identical), RNY3P9 (79% identical), Y_RNA (79% identical), RNY3P14 (78% identical), RNY3P16 (78% identical), Y_RNA (78% identical), and 93 more.